LIPE (lipase E, hormone sensitive type)
Description:
Lipase with broad substrate specificity, catalyzing the hydrolysis of triacylglycerols (TAGs), diacylglycerols (DAGs), monoacylglycerols (MAGs), cholesteryl esters and retinyl esters. Shows a preferential hydrolysis of DAGs over TAGs and MAGs and preferentially hydrolyzes the fatty acid (FA) esters at the sn-3 position of the glycerol backbone in DAGs. Preferentially hydrolyzes FA esters at the sn-1 and sn-2 positions of the glycerol backbone in TAGs (By similarity). Catalyzes the hydrolysis of 2-arachidonoylglycerol, an endocannabinoid and of 2-acetyl monoalkylglycerol ether, the penultimate precursor of the pathway for de novo synthesis of platelet-activating factor (By similarity). In adipose tissue and heart, it primarily hydrolyzes stored triglycerides to free fatty acids, while in steroidogenic tissues, it principally converts cholesteryl esters to free cholesterol for steroid hormone production (By similarity).
Synonyms: HSL; REH; AOMS4; FPLD6; LHS
Tractability: Small molecule: a high-quality ligand is known; it belongs to a druggable protein family. Antibody: UniProt places it where antibodies can reach, with high confidence; its Gene Ontology location is reachable by antibodies, with medium confidence. PROTAC: ubiquitination databases record sites on it; its protein half-life has been measured; a small molecule that binds it is known.
Target class: Enzyme; Hydrolase
Chemical probes: HSL-IN-1
Gene: Protein-coding gene on chromosome 19 (42,401,497 to 42,427,388, reverse strand). Ensembl gene ENSG00000079435.
Subcellular location: Cell membrane; Membrane, caveola; Cytoplasm, cytosol; Lipid droplet
Subcellular location (Human Protein Atlas): Cytosol
Pathways (Reactome):
Gene expression (Transcription): MLL4 and MLL3 complexes regulate expression of PPARG target genes in adipogenesis and hepatic steatosis
Metabolism: Triglyceride catabolism
Gene Ontology:
Molecular function: all-trans-retinyl-palmitate hydrolase, all-trans-retinol forming activity; diacylglycerol lipase activity; protein binding; retinyl-palmitate esterase activity; sterol ester esterase activity; triacylglycerol lipase activity; monoacylglycerol lipase activity; acetylalkylglycerol acetylhydrolase activity; hydrolase activity; lipase activity
Biological process: diacylglycerol catabolic process; ether lipid metabolic process; lipid catabolic process; protein phosphorylation; triglyceride catabolic process; cholesterol metabolic process; retinol metabolic process
Cellular component: cytosol; plasma membrane; lipid droplet; membrane; caveola
Genetic constraint (gnomAD): Loss-of-function variants: 66 observed, 86.95 expected, observed/expected ratio (o/e) 0.76, 90% interval 0.62 to 0.93. The upper end of that interval is the gene's LOEUF score, 0.93, which puts it in group 3 of 6, group 1 being the genes least tolerant of losing a copy. Missense variants: 1,343 observed, 1,405.6 expected, observed/expected ratio (o/e) 0.96, 90% interval 0.91 to 1. Synonymous variants: 567 observed, 610 expected, observed/expected ratio (o/e) 0.93, 90% interval 0.87 to 1.
Gene-disease validity (ClinGen):
ClinGen rates the evidence that LIPE causes each of these diseases.
LIPE-related familial partial lipodystrophy (autosomal recessive): Definitive.
Homologues: Orthologues: chimpanzee LIPE (99% identical), macaque LIPE (93% identical), rabbit LIPE (77% identical), pig LIPE (76% identical), mouse Lipe (74% identical), rat Lipe (72% identical), dog LIPE (64% identical), guinea pig LIPE (62% identical), tropical clawed frog lipe (43% identical), zebrafish lipeb (41% identical), zebrafish lipea (34% identical), Drosophila melanogaster Hsl (25% identical), and 1 more.